SLC60A1 (solute carrier family 60 member 1)
Synonyms: MFSD4; MFSD4A; DKFZp761N1114; FLJ34577; UNQ3064; FLJ25004
Tractability: Antibody: UniProt predicts a signal peptide or a membrane-spanning region.
Gene: Protein-coding gene on chromosome 1 (205,568,833 to 205,602,918, forward strand). Ensembl gene ENSG00000174514.
Subcellular location: Membrane
Gene Ontology:
Molecular function: transmembrane transporter activity
Biological process: transmembrane transport
Cellular component: membrane
Genetic constraint (gnomAD): Loss-of-function variants: 30 observed, 46.63 expected, observed/expected ratio (o/e) 0.64, 90% interval 0.48 to 0.87. The upper end of that interval is the gene's LOEUF score, 0.87, which puts it in group 3 of 6, group 1 being the genes least tolerant of losing a copy. Missense variants: 516 observed, 635.81 expected, observed/expected ratio (o/e) 0.81, 90% interval 0.75 to 0.87. Synonymous variants: 281 observed, 276.83 expected, observed/expected ratio (o/e) 1.02, 90% interval 0.92 to 1.12.
Homologues: Orthologues: chimpanzee MFSD4A (99% identical), macaque MFSD4A (99% identical), dog MFSD4A (92% identical), pig MFSD4A (91% identical), rabbit MFSD4A (89% identical), guinea pig MFSD4A (88% identical), mouse Mfsd4a (85% identical), rat Mfsd4a (84% identical), tropical clawed frog mfsd4a (60% identical), zebrafish mfsd4aa (54% identical), zebrafish mfsd4ab (53% identical). Paralogues in human: SLC60A2 (21% identical).
Diseases named in the same sentence as SLC60A1 in open-access papers:
SLC60A1 is named in the same sentence as 11 diseases in open-access papers, as found by Europe PMC text mining. Sharing a sentence is not in itself a finding about the gene and the disease.
SLC60A1 shares sentences with these, for which no sentence is quoted: gastric cancer (8 papers); tumor (7); nasopharyngeal carcinoma (3); cancer (2); breast carcinoma (1); esophageal carcinoma (1); liver cancer (1); lymph node metastasis (1); metastasis (1); Parkinson's (1); vitiligo (1).